ENSG00000238902
Synonyms: LOC124906347
Gene: Small nucleolar RNA gene on chromosome 3 (192,534,009 to 192,534,112, reverse strand). Ensembl gene ENSG00000238902.
Gene Ontology:
Biological process: RNA processing
Cellular component: nucleolus
Homologues: Paralogues in human: SNORD13D (88% identical), SNORD13 (86% identical), SNORD13E (86% identical), SNORD13P1 (86% identical), SNORD13P3 (86% identical).